EGFR (epidermal growth factor receptor)
Diseases named in the same sentence as EGFR in open-access papers (continued):
Sharing a sentence is not in itself a finding about the gene and the disease.
gastric cancer (continued). "For instance, HeLa cells and MKN45 gastric cancer cells transfected to overexpress EGFR display higher sensitivity to drugs that trigger the PA/PDE4/PKA pathway, compared with their non-transfected counterparts." (PMID 34298835, 2021). "For instance, ctDNA analysis has been successfully used to detect resistant mutations in genes such as EGFR, ERBB2, PIK3CA, and RAS, in various cancers including NSCLC, CRC, and gastric cancer." (PMID 33673461, 2021). "We identified a novel signaling axis that modulates geminin expression through LPA-induced EGFR (Y1173) transactivation in gastric cancer cells." (PMID 34658851, 2021). "We provided evidence that LPA-induced EGFR transactivation in gastric cancer cells promoted efficient DNA synthesis, cell-cycle progression through the S phase, and cell proliferation." (PMID 34658851, 2021). "A study of gastric cancer patients detected a high frequency of mutations in MLL4, ERBB3, FBXW7, MLL3, mtor(RPTOR), NOTCH1, PIK3CA, KRAS, ERBB4 and EGFR." (PMID 33909629, 2021). "Other findings indicated that exosome-transferred EGFR modulates liver microenvironment to trigger metastatic gastric cancer development." (PMID 34592904, 2021). "In two of the tested gastric cancer cell lines, tyrosine phosphorylation of EGFR was increased in the presence of LPA." (PMID 34658851, 2021). "lncRNA UCA1 downregulated miR-7, influencing the EGFR axis in gastric cancer cells resistant to hypoxia." (PMID 33806891, 2021). "They found that lapatinib (a dual EGFR and HER2 TKI)-resistant HER2-posititve gastric cancer cells upregulated phosphorylation of EGFR/HER2, and MET appeared to be closely related to the activation of PI3K/AKT and ERK1/2." (PMID 34356110, 2021). "Association between dynamic contrast-enhanced magnetic resonance imaging perfusion histogram parameters and epidermal growth factor receptor expression in different Lauren classifications of advanced gastric cancer." (PMID 35069035, 2021). "Activation of EGFR is responsible for up to 30% gastric cancer cases, in which increased EGFR expression or mutant EGFR is responsible for 5–10% patients and correlates with microsatellite instability molecular subtypes." (PMID 34434889, 2021). "More importantly, miR-7-5p was verified to target EGFR, which has the capability to regulate gastric cancer cell proliferation and apoptosis through regulation of downstream pathways." (PMID 33768139, 2021). "For example, the high activation status of EGFR and HER2 is associated with increased PD-L1 expression in gastric cancer cells and patient tumor tissues." (PMID 33807608, 2021). "Thereby, overexpression of mutant EGFR and HER-2 is highly associated with metastases and poor prognosis in gastric cancer patients." (PMID 34434889, 2021). "They demonstrated that exosomes derived from gastric cancer transport EGFR to the liver and such EGFR are ultimately incorporated into liver stromal cells’ plasma membrane." (PMID 33855679, 2021). "In gastric cancer cells, besides targeting the EGFR pathway, miR-7 targets the IGF1R and downstream RELA and FOS." (PMID 33806891, 2021). "BBR was found to suppress the activation of the epidermal growth factor receptor (EGFR) in gastric cancer tumors." (PMID 34885950, 2021). "It has been demonstrated that S1P induces EGFR expression in vascular smooth muscle cells or directly trans-activates EGFR in gastric cancer cells." (PMID 34201962, 2021). "The anti-epidermal growth factor receptor monoclonal antibody cetuximab facilitates the action of TRAIL in gastric cancer cells by promoting death receptor 4 clustering and FADD protein translocation into lipid rafts." (PMID 33450869, 2021). "Previous study has confirmed that the positive crosstalk between CXCR4 and EGFR increases the migration ability in gastric cancer." (PMID 34555268, 2021).
gastric cancer (continued). "Our previous data also demonstrated that CMTM3 suppressed the metastasis of gastric cancer through the EGFR/STAT3/EMT signaling pathway by interacting with Rab5." (PMID 34560882, 2021). "Less than 6% of the normal gastric tissues demonstrated EGFR expression, whereas EGFR was expressed in 41.8–57.7% of gastric cancers by immunohistochemistry (IHC) analysis." (PMID 36405499, 2021). "Zhang et al82 identified the translocation of epidermal growth factor receptor (EGFR) in hepatotropic metastasis of gastric cancer." (PMID 33145869, 2021). "Knockdown of GALNT2 in gastric cancer cells resulted in decreased Tn antigen and increased phosphorylation of EGFR." (PMID 34069424, 2021). "EGFR over expression is not only a prognostic indicator in gastric cancer, but also can be used as a basis for personalized treatment." (PMID 34485109, 2021). "Further, ZHU’s lab showed TSPAN8 acts as an oncogene in gastric cancer and promotes gastric cancer cell proliferation and invasion partially through EGFR signaling." (PMID 34222025, 2021). "The upregulation of epidermal growth factor (EGF), its receptor (EGFR), and ErbB2 protein in gastric mucosa plays an important role in the occurrence and development of gastric cancer." (PMID 34824590, 2021). "And some researchers have found that miR-138-5p can hinder the proliferation and invasion of gastric carcinoma by mediating epidermal growth factor receptor (EGFR)." (PMID 34532282, 2021). "Targeted therapy based on anti-EGFR monoclonal antibodies (mAb) e.g., nimotuzumab, plus irinotecan, a common medication for gastric cancer treatment, showed potential improvement in EGFR positive patients of advanced gastric cancer." (PMID 32560537, 2020). "The AKT pathway was blocked by the EGFR signaling to suppress the invasion and growth of gastric cancer cells." (PMID 32963532, 2020). "Human epidermal growth factor receptor 2 (HER-2), a tyrosine kinase receptor assigned to the family of epidermal growth factor receptor (EGFR), is a crucial gastric cancer therapeutic target encoded by the c-erbB2 proto-oncogene located on chromosome 17q212." (PMID 33173435, 2020). "The model captures the EGFR, ERK and AKT signaling pathways in two gastric cancer cell lines with different mutation patterns." (PMID 32119655, 2020). "Among gastric cancer, 2–35% of cases are reported to have EGFR protein overexpression and/or gene amplification, while 9–38% of cases are reported to have HER2 overexpression." (PMID 32850413, 2020). "Anti-EGFR–based therapies among patients found to have EGFR amplification by ctDNA analysis achieved responses in ~55% of patients (including patients with gastric cancer)." (PMID 32850413, 2020). "Intertumoral heterogeneity among actionable biomarkers including ERBB2, FGFR2 and EGFR has been observed to occur under therapeutic pressure in advanced gastric cancer." (PMID 32158697, 2020). "It was indeed demonstrated that the inflammatory cytokines IL-1β and IL-8, but TGFβ also induced EGFR trans-activation in gastric cancer cells, particularly via soluble amphiregulin and HB-EGF." (PMID 32698506, 2020). "EV‐delivered EGFR educates the liver microenvironment and promotes liver metastasis of gastric cancer." (PMID 33304472, 2020). "According to the p value, EGFR tyrosine kinase inhibitor resistance is considered to be the most important downstream signaling pathway for members of the B7 family in gastric cancer." (PMID 32025206, 2020). "Overall, multiple studies have been conducted with the use of anti-EGFR therapies for gastric cancer patients." (PMID 32850413, 2020). "The ATTAX3 phase II trial tested the addition of panitumumab to docetaxel, cisplatin, and fluoropyrimidine (DCF) in EGFR-unselected advanced gastric cancer patients." (PMID 32850413, 2020).
gastric cancer (continued). "The activation of M3R results in transactivation of EGFR, thus promoting cell proliferation and inducing phosphorylation of ERK1/2 and AKT; conversely EGFR inhibition arrests the acetylcholine-induced gastric cancer proliferation." (PMID 33120929, 2020). "The correlation between EGFR overexpression and poor prognosis provides a strong rationale for the employment of EGFR targeted therapies combined with standard of care in advanced gastric cancer." (PMID 32850413, 2020). "Alterations in RTK activities, including EGFR, HER2 (ErbB2, EGFR2), and MET (HGFR), are associated with gastric cancer progression." (PMID 32005975, 2020). "There is still also considerable room for improvement in treating EGFR-positive gastric cancers; however, the recognition of the role of NGS, machine learning/artificial intelligence, and combination strategies will hopefully continue to improve survival." (PMID 32850413, 2020). "The authors backed this research up with clinical data of gastric cancer patients, demonstrating upregulation of EGFR in the primary tumour, in serum EVs and liver tissue compared to controls." (PMID 33143170, 2020). "Previous phase II and III clinical trials using EGFR-targeted agents (cetuximab, panitumumab, nimotuzumab, gefitinib) in gastric cancer were terminated due to insignificant survival advantage." (PMID 32070411, 2020). "Other signaling pathways promoting cell proliferation in human gastric cancer cells, such as epidermal growth factor receptor (EGFR) signaling and Akt pathway, have been demonstrated to be regulated by M3R signaling." (PMID 32733896, 2020). "A select number of gastric cancers harbor alterations in EGFR and/or have amplification/overexpression in the HER2; 2–35 and 9–38%, respectively." (PMID 32850413, 2020). "A substantial number of studies have demonstrated that EGFR overexpression has been correlated with more malignant phenotypic state and dismal clinical outcomes in gastric cancer patients, suggesting EGFR as a therapeutically exploitable target." (PMID 32070411, 2020). "Many of the ongoing EGFR inhibitor trials require gastric cancer patients to be tested for EGFR-positivity prior to entry into the study." (PMID 32850413, 2020). "EGFR expressed on gastric carcinoma sEVs is transferred to primary liver cells, where it colocalises with E-Cadherin and induces a decrease in the expression of miR-26a and miR-26b." (PMID 33228060, 2020). "Positive expression rates of HER2/c-erbB-2 and EGFR in gastric cancer tissue were significant higher than that of normal gastric tissue in patients with gastric cancer." (PMID 33817143, 2019). "Specifically, gastric cancer cells depleted of SPG20 showed increased EGFR expression and phosphorylation of kinase involved in the MAPK signaling." (PMID 31194837, 2019). "Upregulated expression and activation of EGFR are correlated with tumor invasion and poor prognosis, indicating that the EGFR signaling pathway is also critical in gastric cancer." (PMID 31608236, 2019). "Analysis of human cancer tissues also revealed a positive correlation between EGFR levels and hypoxia in both colon and stomach cancer samples." (PMID 31717697, 2019). "Accordingly, overexpression of GPAA1 profoundly promoted the proliferation of gastric cancer cells, an effect that was counteracted by the administration of trastuzumab, a blocker simultaneously targeting EGFR and ERBB2." (PMID 31118109, 2019). "A study showed that combination therapy with trastuzumab (anti-HER2 antibody) and cetuximab (anti-EGFR antibody) demonstrated good anti-tumor activity in gastric cancer PDX models." (PMID 30952931, 2019). "EGFR expression has been correlated with shorter overall survival, advanced stages of tumor, and lymph node metastasis in gastric cancer." (PMID 30621788, 2019). "H Huang’s study indicated dopamine D2 receptor suppresses invasion and migration of gastric cancer cells via inhibition of EGFR/AKT/MMP-13 pathway." (PMID 31164161, 2019).
gastric cancer (continued). "The present study was designed to investigate relationship of a new discovered cytoskeleton regulator MICAL‐L2 and the endogenous epidermal growth factor receptor (EGFR) signalling pathways in gastric cancer cell migration." (PMID 31034158, 2019). "On the other hand, there is currently no information available about the relationship between RNA and protein expression levels in EGFR in gastric cancer." (PMID 31602266, 2019). "The protein is involved in several oncogenic signaling pathways, such as the Wnt/β-catenin, Rho GTPase, and EGF/EGFR, whereby it plays a role in many tumors, including gastric cancer." (PMID 31212809, 2019). "Our results indicate that, at least in part, MICAL‐L2 promotes gastric cancer cell migration via EGFR‐dependent activation of HSP27/cytoskeleton and HSP27/β‐catenin signalling." (PMID 31034158, 2019). "In all, these findings demonstrated to the best of our knowledge, the up‐regulation of MICAL‐L2 in gastric cancer cells is attributed to EGFR stability in a Cdc42‐dependent manner." (PMID 31034158, 2019). "We utilised our original antitumor compound-related gene expression database and identified EGFR inhibitors, such as afatinib and erlotinib, as agents that target drug-tolerant CD44v9-positive cells in gastric cancer." (PMID 31607750, 2019). "HER2/c-erbB-2 and EGFR expression were related to the prognosis of gastric cancer patients and can be used as biomarkers of prognosis." (PMID 33817143, 2019). "Recently, miR-7-5p has been shown to inhibit invasion and metastasis by downregulating epidermal growth factor receptor (EGFR) expression in gastric cancer cells." (PMID 31832068, 2019). "In recent years, the human epidermal growth factor receptor (ErbB) family has been extensively investigated in gastric cancer." (PMID 31850207, 2019). "In the present study we assessed the probable correlation between concomitant EGFR and ErbB3 expression and prognosis in gastric cancer." (PMID 30621788, 2019). "In summary, by utilising our in silico drug screening approaches, we identified EGFR inhibitors, such as afatinib, as potential agents to target pre-existing drug-tolerant gastric cancer cells." (PMID 31607750, 2019). "To date, the gastric cancer-related potential therapeutic targets include EGFR, VEGF, MET, FGFR, PI3K/mTOR, and HDAC." (PMID 31816819, 2019). "The present study was designed to define the prognostic importance of HER-2, IGF-1R, PTEN, and EGFR in gastric cancer patients treated with postoperative chemoradiation therapy." (PMID 31318186, 2019). "Overall, the clinical data supported our in vitro results revealed a positive link between MICAL‐L2 and EGFR protein expression in gastric cancer." (PMID 31034158, 2019). "An in silico drug screening approach with our database successfully identified epidermal growth factor receptor (EGFR) inhibitors as agents that can target drug-tolerant CD44v-positive gastric cancer cells." (PMID 31607750, 2019). "Our results indicated a tumor-suppressive role of miR-1296-5p through the translational repression of oncogenic CDK6 and EGFR in gastric cancer." (PMID 30530570, 2019). "Reduced miR-7 expression dramatically enhances growth, invasion, and metastasis of cancer cells and contributes to gastric cancer development and progression by targeting Epidermal Growth Factor Receptor (EGFR) or insulin-like growth factor-1 receptor." (PMID 31200531, 2019). "In MKN45 gastric cancer cells, a molecular complex comprised of integrin α6β4, EGFR, and galectin-3 has been reported." (PMID 31052260, 2019). "We identified epidermal growth factor receptor (EGFR) inhibitors as agents that can target CD44v9-positive cell populations in gastric cancer PDCs." (PMID 31607750, 2019). "Our previous results indicated that cGMP-activated PKG II inhibited the growth of gastric cancer cells through blocking EGFR activation." (PMID 31350342, 2019).
gastric cancer (continued). "Increased expression of MICAL‐L2 in gastric cancer cells up‐regulated EGFR protein level, accompanied by the increase of cell migration, whereas silencing MICAL‐L2 down‐regulated EGFR and inhibited cell migration." (PMID 31034158, 2019). "EGFR was mainly expressed in the membrane and cytoplasm of gastric cancer cells with uniform distribution of brown and yellow granules." (PMID 33817143, 2019). "In conclusion, this study suggests that IGF-1R, EGFR, and cigarette smoking can be used as additional prognostic factors to the previously known prognostic factors in gastric cancer patients treated with chemoradiation therapy." (PMID 31318186, 2019). "Although, the correlation between EGFR overexpression and poor prognosis was observed in many studies, EGFR structural alterations are rare in gastric cancer." (PMID 30621788, 2019). "In gastric cancer, leptin induces tyrosine phosphorylation of EGFR resulting in transactivation of this cascade." (PMID 30634942, 2019). "Given the importance of EGFR signaling in cancer cell growth and tumor progression, our study highlights a potential new therapeutic target for gastric cancer." (PMID 31492173, 2019). "We further explored the signalling pathways by which MICAL‐L2 affects gastric cancer cell migration via EGFR activation." (PMID 31034158, 2019). "We used MKN45 to assess overall prediction accuracy, even though it represents a gastric cancer cell line, because signaling pathways such as EGFR-MAPK pathways proteins signaling are highly conserved across tissue and species." (PMID 30615629, 2019). "There was a direct correlation between EGFR and ErbB3 expression highlighting that these heterodimers have a significant prognostic role in gastric cancer." (PMID 30621788, 2019). "Previous studies have confirmed that Cbl increases the chemosensitivity of gastric cancer cells by enhancing the epidermal growth factor receptor (EGFR) and mitochondrial signaling pathways." (PMID 31976317, 2019). "HER2/c-erbB-2 and EGFR protein expression was examined by immunohistochemical assay in gastric cancer tissue and corresponding paired normal gastric tissue of 67 patients of gastric carcinoma." (PMID 33817143, 2019). "EGFR overexpression is observed in various human malignancies including lung, breast, colon, and gastric cancers." (PMID 31318186, 2019). "Zhen et al50 also indicated that knockdown of EGFR reduced cell invasion of gastric cancer and led to decreased expression of MMP‐9." (PMID 31638339, 2019). "Previous studies revealed that Cbl-b increases the sensitivity of gastric cancer cells by enhancing the epidermal growth factor receptor (EGFR) and mitochondria mediated signaling pathways in gastric cancer." (PMID 29940895, 2018). "In conclusion, induction of NOX4 expression by detachment promotes anoikis resistance of gastric cancer through ROS generation and downstream upregulation of EGFR, which is critical for the metastatic progression of gastric cancer." (PMID 30237423, 2018). "Proteins interacting with CYTOR had been investigated in other cancer types; for example, EZH2 and EGFR were reported to interact with CYTOR in gastric cancer." (PMID 30064438, 2018). "When compared with gefitinib-sensitive gastric cancer samples (n = 12), the expression of p-EGFR decreased and the expression of integrin β4 significantly upregulated in gefitinib-resistant samples (n = 38)." (PMID 29618949, 2018). "High levels of phosphorylation are observed as a result of RTK amplification and overexpression in few cases which are indication specific like Her2 in breast and gastric cancer, MET in gastric cancer and EGFR in lung and gastric cancer." (PMID 29989001, 2018). "The prediction identified three microRNAs (miR-21, miR-145 and miR-148a) and five gastric cancer-specific target genes (EGFR, KLF4, DNMT1 and AGO4) which also showed strong correlation with lncRNAs in regression analysis." (PMID 29719612, 2018).